COL1A2 (collagen type I alpha 2 chain)
Diseases named in the same sentence as COL1A2 in open-access papers (continued):
Sharing a sentence is not in itself a finding about the gene and the disease.
gastric cancer (continued). "Consistent with previous reports, the present study demonstrated that COL1A1 and COL1A2 mRNA expression levels were highly expressed in gastric cancer specimens compared to normal gastric epithelium by real-time quantitative PCR analysis." (PMID 27894325, 2016). "The correlations between COL1A1 and COL1A2 expression and clinicopathological parameters were analyzed in 45 gastric cancer patients undergoing surgery." (PMID 27894325, 2016). "Then, analysis was performed to correlate COL1A1 and COL1A2 mRNA expression and clinicopathological parameters and overall survival time in gastric cancer." (PMID 27894325, 2016). "In the present study, we demonstrate the relationships between clinicopathological parameters and overall survival time and COL1A1 and COL1A2 mRNA expression in gastric cancer." (PMID 27894325, 2016). "IHC showed that COL1A2 was highly expressed in gastric cancer and GC cells." (PMID 41917621, 2026). "We note that key nodes such as COL1A1, COL1A2, JUN, MMP9, APOE, and FOS displayed strongest strength of interactions in the network, suggesting that these genes are key genes associated with other proteins in gastric cancer." (PMID 39044041, 2024). "COL1A2 was confirmed to be significantly overexpressed in gastric cancer tissues." (PMID 36171259, 2022). "However, the specific role of COL1A2 in gastric cancer (GC) cell resistance to apatinib, a highly selective small-molecule inhibitor of vascular endothelial growth factor receptor 2, has not been investigated before." (PMID 35242497, 2022). "LIFR-AS1 modulates COL1A2 to promote gastric cancer cell proliferation and migration by miR-29a-3p." (PMID 36316703, 2022). "Additionally, COL1A1 highly expressed in human breast and gastric cancer, while COL1A2 highly expressed in gastric cancer, and affected the prognosis." (PMID 33828526, 2021). "Our study identified COL1A1 and COL1A2 as potential gastric cancer prognostic biomarkers." (PMID 32509452, 2020). "Over expression of COL1A2 was important for the pathogenesis of gastric cancer, but high expression of this gene may be involved in development of GBM." (PMID 31137733, 2019). "The group of Li J also supposed that COL1A1 and COL1A2 might predict poor clinical outcomes in gastric cancer patients." (PMID 31409759, 2019). "Recently, multiple collagen family members were hypothesized to be involved in carcinogenesis, among which COL1A2 expression was illustrated to be positively related to tumor size and depth of invasion in gastric cancer (Li, Ding, & Li, 2016)." (PMID 31304688, 2019). "We find that COL1A1 might have its potential as a monitoring factor to screen early gastric cancer, and COL1A1 and COL1A2 might predict poor clinical outcomes in gastric cancer patients." (PMID 27894325, 2016). "Another in‐silico‐based study that analyzed multiple publicly available datasets identified collagen genes COL1A1, COL1A2, COL3A1, and COL5A1 as key CAF markers in gastric cancers." (PMID 39245631, 2025). "I with a logFC >1, we generated a gene signature of iGC stage progression (intestinal-type gastric cancer progression signature - iGCPS), composed of APOD, COL1A2, GEM, FSTL1, LUM and SPARC." (PMID 39563861, 2024). "A previous study showed that seven collagen genes (COL1A2, COL4A1, COL6A2, COC6A1, COL4A2, and COL11A1) were highly expressed in gastric cancer tissues, consistent with our findings." (PMID 39220121, 2024). "Among the prominent six genes highlighted in the protein-protein interaction network, higher expression levels of COL1A1, COL1A2, and APOE have also been confirmed to contribute to shorter survival in gastric cancer." (PMID 39044041, 2024). "The expression of COL1A2, COL6A3, and THBS2 genes leads to the development, migration, and invasion of gastric cancer cells, and reduces apoptosis through the PI3K-Akt pathway." (PMID 37361568, 2023).
gastric cancer (continued). "Eight out of 38 upregulated genes in gastric cancer (ASPN, COL1A1, COL1A2, COL3A1, COL5A1, FAP, FN1, and SPARC) overlapped with the CAF markers list (circos plot on the left)." (PMID 35739492, 2022). "We identified ECM components COL1A1, COL1A2, COL3A1, COL5A1, FN1, and SPARC as the pivotal CAF markers in gastric cancer, which were separately reported as biomarkers of gastric cancer in different studies." (PMID 35739492, 2022). "In this study, we identified the six key CAF markers namely COL1A1, COL1A2, COL3A1, COL5A1, FN1, and SPARC in gastric cancer that can be used as predictors of CAF infiltration and prognostic biomarkers in gastric cancer." (PMID 35739492, 2022). "Our study revealed the COL1A1, COL1A2, COL3A1, COL5A1, FN1, and SPARC as the key CAF markers in gastric cancer." (PMID 35739492, 2022). "In gastric cancer tissues, the average score of expression of ITGB1 was 7.8, and the average score of expression of COL1A2 was 7.0." (PMID 34326374, 2021). "COL1A2, a member of group I collagen family, has once been reported as a target of Let-7g thus inhibiting cell migration in HCC and gastric cancer cell proliferation." (PMID 32849813, 2020). "Hence the module analysis strengthened the connection of the six CAF markers: COL1A1, COL1A2, COL3A1, COL5A1, FN1 and, SPARC, with the 3 KEGG pathways: ECM-receptor interaction, focal adhesion and, PI3K-Akt signaling pathway in gastric cancer." (PMID 35739492, 2022). "This experiment first verified the abnormal expression of differential genes in gastric cancer tissues, then constructed a PPI network, calculated its key nodes as ITGB1 and COL1A2, and finally examined its correlation with the survival rate of patients with gastric adenocarcinoma." (PMID 34326374, 2021). "In 2018, a study found that the silencing of COL1A2 could inhibit the proliferation, migration, and invasion of gastric cancer through regulating PI3K/AKT signaling pathway, revealing the potency of COL1A2 in HCC." (PMID 32849813, 2020). "We demonstrate that COL1A1 and COLA2 are overexpressed in gastric cancer, high COL1A1 might be a monitoring factor for early gastric cancer, and high COL1A1 and COL1A2 mRNA expression could be prognostic factors predicting overall survival time." (PMID 27894325, 2016). "The expression of COL1A2 was analysed by immunohistochemistry/immunocytochemistry (IHC/ICC) in 150 patients with gastric cancer and a GC cell line." (PMID 41917621, 2026). "These transcription factors play an important role in the progression of GC; for example, EP300 has the ability to regulate the expression of COL1A2 to control the drug resistance of gastric cancer cells to apatinib." (PMID 37735667, 2023). "Through immunohistochemical analysis of tumor samples and adjacent tissues of gastric cancer patients, the results showed that in normal tissues adjacent to cancer, the average score of ITGB1 expression was 1.6 points, and the average score of COL1A2 expression was 2.2 points." (PMID 34326374, 2021). "However, the clinical significance of COL1A1 and COL1A2 in gastric cancer remains unclear, and the expression of COL1A1 and COL1A2 in normal epithelium, premalignant, and tumor lesions of the stomach is rarely mentioned." (PMID 27894325, 2016). "However, the expression of COL1A1 and COL1A2 in malignant, premalignant, and normal gastric tissues and their clinical significances in gastric cancer have not been elucidated." (PMID 27894325, 2016). "COL1A2 exhibits altered expression in several tumor types most notably gastric cancer." (PMID 25327563, 2014). "For example, collagen type I alpha 2 chain (COL1A2) was suggested to be a novel biomarker to enhance the clinical prediction of gastric cancer, and collagen type X alpha 1 (COL10A1) might be a key independent predictor of poor over survival of GC patients." (PMID 34506251, 2021).
breast carcinoma (41 papers, 1998 to 2026). "In functional assays, higher COL1A2 expression was associated with reduced sensitivity to docetaxel in HR+/HER2- breast cancer cells." (PMID 41846871, 2026). "In contemporary literature, a transcriptional signature including COL1A2 was associated with reduced overall survival in breast cancer." (PMID 38928454, 2024). "For example, in breast cancer, up-regulation of COL1A2 has been associated with increased tumor invasiveness and metastasis." (PMID 38913913, 2024). "COL1A2 has been linked to reduced overall and recurrence-free survival in breast cancer." (PMID 40867231, 2025). "RNA sequencing and PPI network analysis identified COL1A2 as significantly overexpressed in HR+/HER2- breast cancer patients with docetaxel resistance." (PMID 41846871, 2026). "There is evidence that COL1A2 promotes metastasis in breast cancer and contributes to poor survival in patients." (PMID 39273514, 2024). "Increased COL1A2 expression has also been reported in many types of cancer, including breast cancer, cervical cancer, and colon cancer." (PMID 37361568, 2023). "The expression data of ECM fiber-encoding genes (e.g., COL1A1, COL1A2, FGA, FGB, FGG, ELN, FN1, and VTN) from 1358 patients with breast cancer were used for Kaplan–Meier overall survival analysis." (PMID 37369642, 2023). "Increased expression of COL1A1 and COL1A2 are considered to influence tumor invasion and progression and are reported in several types of cancer, such as gastric, colorectal, and breast cancer." (PMID 35159353, 2022). "COL1A2 was found to be differentially upregulated in breast cancer cells compared to normal breast tissue." (PMID 32525891, 2020). "Two genes (DAXX, ADAM17) are involved in ovarian cancer and three genes (TNFRSF1A, TIMP4, COL1A2) are exclusive to breast cancer." (PMID 31205821, 2019). "Hypermethylation of COL1A2 has been described in breast carcinomas, melanomas, and medulloblastomas." (PMID 29361757, 2018). "Aberrant COL1A2 promoter methylation has been detected in various cancer types, such as breast carcinoma, medulloblastoma, and melanoma." (PMID 27027429, 2016). "While these other two studies were done on different cancer types (breast cancer and lymphomas), one common methylated gene, COL1A2 was identified." (PMID 22028813, 2011). "Evidence for COL1A2 aberrant promoter methylation has been described in different cancer cells such as breast cancer, medulloblastoma, hepatoma, colorectal cancer and more recently in melanoma." (PMID 22028813, 2011). "The computational pipeline was applied to a panel of 45 breast cancer cell lines, and the protocol identified a list of 58 genes, including COL1A2, TOP2A, TFF1, and VAV3, whose key roles in epigenetic regulation are consistent with known literature." (PMID 20525369, 2010). "It is noteworthy that two of the genes that were found to predict poor survival of prostate and breast cancer patients in the present study (PTTG1 and COL1A2), form part of a 17-gene signature associated with metastases." (PMID 17183660, 2006). "Besides, COL1A1 expressed by ovarian cancer fibroblasts promoted migration and invasion of ovarian cancer cells and COL1A2 was identified as a hub node in the stromal module of breast cancer." (PMID 39695086, 2024). "Similarly, numerous tumor-associated genes, including COL1A2, PD-L1, HOXB cluster genes, and CLCA2, are epigenetically regulated in breast cancer cells." (PMID 36768307, 2023). "Interestingly, the expression profile of Ccl2, Col1a1, Col1a2, and Itgam was very close to most of the breast cancer samples, with a degree of variability among samples." (PMID 37243196, 2023). "Evaluation of differentially expressed genes between primary breast cancer and brain metastatic tissues showed that the COL1A2 gene is down-regulated in brain metastatic compared with primary pairs, indicating that this gene is critical to breast cancer progression to the brain." (PMID 35045088, 2022).
breast carcinoma (continued). "Our findings suggest that inhibition of COL1A2 may be a potential therapeutic strategy in breast cancer; although the ubiquitous expression of this protein may present some challenges." (PMID 32525891, 2020). "Of the other identified proteins associated with breast cancer, COL1A1 and COL1A2, the two components of type I collagen, were shown to be upregulated in invasive breast cancer, with a potential role in spinal metastasis, although not proposed as potential targets." (PMID 31139569, 2019). "The research in mouse models of breast cancer indicates that COL1A1 is a key extracellular matrix gene and is identified with copy number alterations through integrative in vitro and in vivo studies, while COL1A2 methylation is associated with ER/PR receptor status in breast cancer cohort." (PMID 38088228, 2024). "According to the xiantao database, COL1A2, COL3A1, FGA, LUM, APOA1, APOH, and COL5A2 were more highly expressed in breast cancer than in normal tissues (p < 0.05), while the opposite pattern was seen for ALB and FBN1 (p < 0.05)." (PMID 37079213, 2023). "Since the COL3A1 and COL1A2 genes are both in the pathway of scavenging by class A receptors, which are important regulators of immune responses to cancer, their co-expression changes in the tumor tissue may help us better understand the immune response processes in breast cancer." (PMID 34252628, 2021). "COL1A1, COL1A2, COL11A1, and COL5A1 have been reported to regulate several cancers, including colorectal cancer, esophageal cancer, hepatocellular carcinoma, renal cell carcinoma, breast cancer, and gliomas." (PMID 38639039, 2024). "When we further interrogated the expression of collagen genes commonly expressed in breast cancer ECM (COL1A1, COL1A2, COL3A1 and COL5A1) we observed decreased endogenous gene expression of these collagens in higher passage TU-BcX-4IC tumors compared to lower passage." (PMID 34370182, 2022).
osteoporosis (41 papers, 2010 to 2025). A condition of reduced bone mass, with decreased cortical thickness and a decrease in the number and size of the trabeculae of cancellous bone (but normal chemical composition), resulting in increased fracture incidence. "The aim of this study was to test the impact of two SNPs of COL1A2 on the risk of osteopenia and osteoporosis in postmenopausal women." (PMID 40563416, 2025). "Our RNA-seq results showed that the expression of the Col1A1, Col1A2, and Vdr genes associated with osteoporosis (as revealed by OMIM disease enrichment analysis) was decreased by H2O2." (PMID 37464093, 2023). "Three patients with mutations in genes encoding type I collagen (COL1A1 and COL1A2) were identified, and their skeletal abnormalities were characterized primarily by osteoporosis, with less common abnormalities in the limb bones and skull." (PMID 35250876, 2022). "Future studies with larger cohorts, more precise genotyping methods, and detailed analyses of gene–environment interactions are warranted to further elucidate the role of COL1A2 and other genetic variants in the pathogenesis of osteoporosis and bone mineral loss." (PMID 40563416, 2025). "Given that type I collagen plays a crucial role in bone strength, this association warrants further investigation to determine whether COL1A2 variants contribute to inherited osteoporosis risk." (PMID 40507792, 2025). "In the COL1A2 gene, located on chromosome 7 (7q21.3), the rs42524 variant [NC_000007.14:g.94413927C>G], found in exon 28, has been studied not only in the context of osteoporosis but also in relation to cardiovascular diseases and metabolic disorders." (PMID 40507792, 2025). "Specific genetic associations of collagens may indicate an increased incidence of healthier aging, in which COL1A1 rs107946 may suggest accelerated osteoporotic-related aging, but COL1A2 rs3917 suggests a reduced risk of osteoporosis." (PMID 37189830, 2023). "It has been reported that the abnormal expression or mutation of COL1A2 may involve in the development of osteopenia and osteoporosis." (PMID 35935376, 2022). "While commonly linked to ageing and environmental factors, osteoporosis can also result from Mendelian monogenic disorders, with mutations in genes such as COL1A1 and COL1A2 impairing bone integrity." (PMID 40772209, 2025). "Monogenic forms, often syndromic, were linked to mutations in genes such as COL1A1, COL1A2, and WNT1, whereas multifactorial osteoporosis, particularly postmenopausal, was associated with variants in LRP5, SOST, VDR, and other GWAS-identified loci." (PMID 40772209, 2025). "The COL1A2 gene is associated with bone mineral density (BMD), and variations in this gene can influence the risk of osteoporosis and fractures." (PMID 40563416, 2025). "Recent studies have reported abnormal expression of COL1A1 and COL1A2 in osteogenesis, osteoporosis, various bone disorders, and multiple cancers." (PMID 41463322, 2025). "Identification of CNVs in genes previously associated with osteoporosis (e.g. RUNX2, COL1A2, and PLS3) has confirmed their importance in bone remodelling." (PMID 36795294, 2023). "We studied a family with severe primary osteoporosis carrying a heterozygous p.Arg8Phefs*14 deletion in COL1A2, leading to haploinsufficiency." (PMID 32722848, 2020). "Importantly, BMSCs isolated from patients with osteoporosis showed a decrease in histone H3K18la lactylation and the expression of the target genes COL1A2, COMP, ENPP1, and TCF7L2." (PMID 37752768, 2023). "In addition, osteoporosis is strongly associated with genetic components of type 1 collagen such as COL1A1 and COL1A2." (PMID 32353054, 2020). "ZNF528 is a novel candidate gene for bone disorders and may function as a transcriptional regulator in pathways affecting bone morphology and contribute to the phenotype of primary osteoporosis in this family together with the COL1A2 deletion." (PMID 32722848, 2020).
osteoporosis (continued). "Moreover, osteoporosis is strongly associated with genetic components of type 1 collagen such as COL1A1 and COL1A2." (PMID 31575827, 2019). "Although both genes have been linked to monogenic forms of osteoporosis, COL1A2 deletions are rare and PLS3 duplications have not been described previously." (PMID 30042735, 2018). "We believe that patients with COL1A2 variants resulting in functional deficits may only exhibit a certain degree of osteoporosis, rather than presenting as OI patients due to attenuated skeletal phenotypes." (PMID 40282376, 2025). "While mutations in COL1A2 rendering premature stop codon usually have no phenotypes in heterozygote, modifying variant may contribute to the phenotypes of primary osteoporosis." (PMID 34394176, 2021). "A genetic panel for over 40 genes involved in osteoporosis was analysed in the family, revealing a VUS in COL1A2." (PMID 36769638, 2023). "Osteoporosis is also known to be strongly related to the genetic components of type I collagen (COL1A1 and COL1A2)." (PMID 34200258, 2021). "As skeletal development or bone formation activity, the markers of osteogenic differentiation of BMSCs, such as RUNX2, COL1a2, and BMPR1B, were decreased in the osteoporosis group." (PMID 27171263, 2016). "Because osteoporosis is a systemic disease and is strongly related to genetic components of type 1 collagen (COL1A1 and COL1A2), we propose that osteoporotic conditions may influence cancellous bone of the skull." (PMID 33071940, 2020). "However, this COL1A2 VUS was inherited from the mother who had relatively unremarkable bone mineral density and the father with osteoporosis was wild-type, indicating a lack of segregation of the COL1A2 variant with the bone phenotype." (PMID 36769638, 2023). "qPCR analysis of the target genes of H3K18la lactylation indicated that the expression of the osteogenic genes COL1A2, COMP, ENPP1, and TCF7L2 was decreased in BMSCs isolated from patients with osteoporosis compared with that in BMSCs from patients without osteoporosis." (PMID 37752768, 2023).